LPCAT1 (lysophosphatidylcholine acyltransferase 1)
Description:
Exhibits acyltransferase activity. Exhibits acetyltransferase activity (By similarity). Activity is calcium-independent (By similarity). Catalyzes the conversion of lysophosphatidylcholine (1-acyl-sn-glycero-3-phosphocholine or LPC) into phosphatidylcholine (1,2-diacyl-sn-glycero-3-phosphocholine or PC). Catalyzes the conversion 1-acyl-sn-glycerol-3-phosphate (lysophosphatidic acid or LPA) into 1,2-diacyl-sn-glycerol-3-phosphate (phosphatidic acid or PA) by incorporating an acyl moiety at the sn-2 position of the glycerol backbone (By similarity). Displays a clear preference for saturated fatty acyl-CoAs, and 1-myristoyl or 1-palmitoyl LPC as acyl donors and acceptors, respectively (By similarity). Involved in platelet-activating factor (PAF) biosynthesis by catalyzing the conversion of the PAF precursor, 1-O-alkyl-sn-glycero-3-phosphocholine (lyso-PAF) into 1-O-alkyl-2-acetyl-sn-glycero-3-phosphocholine (PAF) (By similarity). May synthesize phosphatidylcholine in pulmonary surfactant, thereby playing a pivotal role in respiratory physiology (By similarity). Involved in the regulation of lipid droplet number and size.
Synonyms: LPCAT-1; LysoPAFAT; AYTL2; PFAAP3; FLJ12443; AGPAT9; AGPAT10; LPLAT8; lpcat
Tractability: Antibody: UniProt places it where antibodies can reach, with high confidence; its Gene Ontology location is reachable by antibodies, with high confidence; UniProt predicts a signal peptide or a membrane-spanning region. PROTAC: ubiquitination databases record sites on it; its protein half-life has been measured.
Target class: Enzyme; Transferase
Gene: Protein-coding gene on chromosome 5 (1,456,480 to 1,524,282, reverse strand). Ensembl gene ENSG00000153395.
Subcellular location: Endoplasmic reticulum membrane; Golgi apparatus membrane; Cell membrane; Lipid droplet
Subcellular location (Human Protein Atlas): Endoplasmic reticulum; Lipid droplets
Pathways (Reactome):
Metabolism: Acyl chain remodelling of PC; Acyl chain remodelling of PG; Synthesis of PA; Synthesis of PC
Immune System: Neutrophil degranulation
Gene Ontology:
Molecular function: 1-acylglycerophosphocholine O-acyltransferase activity; 1-acylglycerol-3-phosphate O-acyltransferase activity; 1-alkylglycerophosphocholine O-acetyltransferase activity; 2-acylglycerol-3-phosphate O-acyltransferase activity; lysophosphatidic acid acyltransferase activity; plasmalogen synthase activity; 1-alkylglycerophosphocholine O-acyltransferase activity; acyltransferase activity; calcium ion binding
Biological process: phosphatidylcholine acyl-chain remodeling; phosphatidic acid biosynthetic process; phosphatidylglycerol acyl-chain remodeling; phospholipid biosynthetic process; phospholipid metabolic process
Cellular component: endoplasmic reticulum; endoplasmic reticulum membrane; lipid droplet; membrane; azurophil granule membrane; Golgi apparatus; Golgi membrane; plasma membrane
Genetic constraint (gnomAD): Loss-of-function variants: 22 observed, 55.67 expected, observed/expected ratio (o/e) 0.4, 90% interval 0.28 to 0.56. The upper end of that interval is the gene's LOEUF score, 0.56, which puts it in group 2 of 6, group 1 being the genes least tolerant of losing a copy. Missense variants: 609 observed, 705.87 expected, observed/expected ratio (o/e) 0.86, 90% interval 0.81 to 0.92. Synonymous variants: 331 observed, 301.42 expected, observed/expected ratio (o/e) 1.1, 90% interval 1 to 1.2.
Homologues: Orthologues: chimpanzee LPCAT1 (99% identical), mouse Lpcat1 (88% identical), rat Lpcat1 (88% identical), pig LPCAT1 (85% identical), dog LPCAT1 (83% identical), guinea pig LPCAT1 (76% identical), macaque LPCAT1 (75% identical), tropical clawed frog lpcat1 (67% identical), zebrafish lpcat1 (62% identical), Drosophila melanogaster LPCAT (34% identical). Paralogues in human: LPCAT2 (43% identical), LPCAT4 (35% identical), GPAT4 (14% identical), GPAT3 (13% identical).
Diseases named in the same sentence as LPCAT1 in open-access papers:
LPCAT1 is named in the same sentence as 85 diseases in open-access papers, as found by Europe PMC text mining. Sharing a sentence is not in itself a finding about the gene and the disease. The quoted sentences say what the papers report.
hepatocellular carcinoma (28 papers, 2014 to 2026). A malignant tumor that arises from hepatocytes. "The overexpression of LPCAT1 mRNA was associated with multiple disorders, including hepatocellular carcinoma, endometrial cancer, pulmonary emphysema, lung carcinoma, epithelioid trophoblastic tumors, and breast carcinoma." (PMID 41007798, 2025). "LPCAT1 is an independent prognostic biomarker and associated with tumor microenvironment, immune cell infiltration, immune checkpoint expression and drug sensitivity in hepatocellular carcinoma." (PMID 36307879, 2022). "LPCAT1 exhibits significant elevations in various types of cancer, including hepatocellular carcinoma, esophageal squamous cell carcinoma, and lung adenocarcinoma." (PMID 41450825, 2025). "Recently, the expression profile of the LPCAT1 enzyme has been studied in various cancerous diseases, including hepatocellular carcinoma, gastric carcinoma, endometrial cancer, lung adenocarcinoma, and breast carcinoma." (PMID 41007798, 2025). "LPCAT1 upregulation is connected to clear renal cell carcinoma, oral squamous cell carcinoma, hepatoma, esophageal cancers, gastric cancers, breast cancers, colorectal cancers and prostate cancers." (PMID 38921447, 2024). "LPCAT1 acts as an independent prognostic biomarker correlated with immune infiltration in hepatocellular carcinoma." (PMID 37294538, 2023). "Using a rat model of hepatocellular carcinoma, we found that LPCAT1 expression was substantially higher in tumor tissues compared to normal tissues." (PMID 37717019, 2023). "HE staining confirmed the successful construction of hepatocellular carcinoma, and immunohistochemistry results showed that the expression of LPCAT1 was significantly higher in HCC than in normal rat liver tissue." (PMID 37717019, 2023). "First, we explored the expression of AGPAT5, LCLAT1, and LPCAT1 in common hepatocellular carcinoma cell lines by data mining in the CCLE database." (PMID 36845084, 2023). "The authors conducted bioinformatics analyses using high throughput RNA sequencing data from TCGA to demonstrate that LPCAT1 is a novel and effective prognostic marker for hepatocellular carcinoma." (PMID 37397555, 2023). "The study reported the highest expression of LPCAT1 in HCCLM3 in hepatocellular carcinoma cells in vitro." (PMID 37717019, 2023). "LPCAT1 is also used in the prognosis of multiple tumors, such as breast cancer, colorectal cancer, and hepatocellular carcinoma." (PMID 37480069, 2023). "Taken together, our results suggest that LPCAT1 plays a tumor-promoting role and the silencing ofLPCAT1 inhibits cell stemness and metastasis in EC, similar to the role of LPCAT1 in hepatocellular carcinoma and oral squamous cell carcinoma." (PMID 35880567, 2022). "In conclusion, SNHG3 was selected as a possible upstream lncRNA for miR-139-5p, thereby affecting the LPCAT1 expression and promoting hepatocellular carcinoma progression." (PMID 35615532, 2022). "Upregulation of LPCAT1 has been observed in clear renal cell carcinoma, oral squamous cell carcinoma, hepatoma, esophageal cancers, gastric cancers, breast cancers, colorectal cancers, and prostate cancers." (PMID 33530546, 2021). "To date, LPCAT1 over-expression has been reported in hepatocellular carcinoma, colorectal adenocarcinoma, prostate cancer and oral squamous cell carcinoma, and has been identified as a contributor to cancer progression, metastasis, and recurrence." (PMID 30791942, 2019). "When we knocked down both LCLAT1 and LPCAT1 in hepatocellular carcinoma cell lines, we could observe a significant increase in the protein level of E-cadherin." (PMID 36845084, 2023). "Additionally, we show that interference with LPCAT1 influences lipoprotein particle secretion from hepatoma cells." (PMID 25491198, 2014).
hepatocellular carcinoma (continued). "In addition, genetic interventions targeting PPM1B/USP10-Y-box binding protein 1 (YBX1) axis or lysophosphatidylcholine acyltransferase 1 (LPCAT1) enhance PANoptosis-related protein activation, effectively suppressing gastric and hepatocellular carcinoma progression." (PMID 40721869, 2025). "However, whether the effect of LPCAT1 on hepatoma cells is consistent with our results still needs to be verified by further in vitro experiments." (PMID 37662906, 2023). "In addition, silencing LPCAT1 inhibited the stemness of hepatocellular carcinoma cells." (PMID 37717019, 2023). "Similarly, higher LPCAT1 expression was reported in several other malignant tumours compared to normal tissues, including colorectal adenocarcinoma, prostate cancer, hepatocellular carcinoma, gastric cancer, breast cancer and oral squamous cell carcinoma." (PMID 28494778, 2017). "Also, knockdown of LPCAT1 decreases lipoprotein secretion by hepatoma cells." (PMID 25491198, 2014). "For example, in hepatocellular carcinoma (HCC), LPCAT1 expression positively correlated with immune infiltrating cells included Macrophages M0, Memory B cells, Activated Dendritic cells, Regulatory T cells, and γδT cells." (PMID 40723289, 2025). "It has been reported that the expression of either LPCAT1 or ENPP2 is increased and some LPCs are decreased in diverse human tumors including hepatoma, melanoma, and acute myeloid leukemia." (PMID 34869922, 2021). "LPCAT1 enzyme and LPC are elevated in several other cancers, including colorectal cancer, hepatocellular carcinoma, gastric cancer and clear cell renal carcinoma." (PMID 32429496, 2020). "Finally, we analyzed the correlation between these transcription factors and stemness-related genes in hepatocellular carcinoma transcriptome data and found a significant correlation between NDRG1 and these transcription factors compared to LPCAT1." (PMID 37717019, 2023). "Interestingly, LPCAT1-TERT fusions has been described in lung adenocarcinoma and in a pediatric hepatocellular carcinoma." (PMID 29312603, 2017). "Similarly, LCLAT1 expression was recently found to be upregulated in hepatocellular carcinoma (HCC), compared to normal liver tissue, and along with AGPAT5 and LPCAT1, was identified as a highly sensitive biomarker that correlated with worse prognosis and overall survival." (PMID 41473749, 2025). "Since double KDs are difficult and phenotypes are weak due to mutual compensation by the isoenzymes, we also analyzed the human hepatoma cell line HuH7, which expresses LPCAT3 and LPCAT1, but no LPCAT2." (PMID 25491198, 2014). "However, the role of LPCAT1 in hepatocellular carcinoma (HCC) has not been understood." (PMID 36307879, 2022).
prostate carcinoma (23 papers, 2012 to 2024). A carcinoma that arises from epithelial cells of the prostate gland. "Prognosis and survival for clear cell renal cell carcinoma, breast cancer and prostate cancer are linked with LPCAT1 expression; it is useful as a diagnostic biomarker for prostate and esophageal cancers." (PMID 38921447, 2024). "For instance, overexpression of LPCAT1 was implicated in clear cell renal cell carcinomas, prostate cancer, esophageal squamous cell carcinoma and lung cancer." (PMID 37294538, 2023). "LPCAT1 is implicated in various cancer types; overexpression of LPCAT1 was recently described in colorectal cancer, prostate cancer, lung cancer, and clear cell renal cell carcinomas." (PMID 34518524, 2021). "For example, elevated lysophosphatidylcholine acyltransferase 1 (LPCAT1) levels are linked with poor prognosis and early tumor recurrence in breast cancer, gastric and colorectal cancer, prostate cancer, ccRCC, liver cancer, and EGFR-dependent glioblastoma." (PMID 33413672, 2021). "LPCAT1 expression is correlated with prognosis and survival in clear cell renal cell carcinoma, breast cancer, and prostate cancer and can be used as a diagnostic marker in prostate cancer and esophageal cancer." (PMID 33530546, 2021). "Moreover, high expression of the LPCAT1 gene has been implicated in the pathology of lung adenocarcinoma, breast cancer, prostate cancer, esophageal squamous cell carcinoma, and HCC, among other cancers." (PMID 36845084, 2023). "LPCAT1 is also responsible for chemoresistance, particularly to paclitaxel in prostate cancer and breast cancer and gefitinib in lung adenocarcinoma." (PMID 38893234, 2024). "In contrast, in prostate cancer and oral squamous cell carcinoma, LPCAT1 increases the production of the platelet-activating factor (PAF)." (PMID 38893234, 2024). "For instance, prostate cancer that is resistant to castration advances due to LPCAT1’s ability to enhance mRNA synthesis as well as PAF production." (PMID 37294538, 2023). "Ruminococcus plays an essential role in prostate cancer progression, possibly through the activation of the “Ruminococcus-LPCAT1-DNA repair” pathway." (PMID 36227107, 2022). "Ruminococcus, which was involved in glycerolphospholipid metabolism, promoted prostate cancer progression by upregulating lysophosphatidylcholine acyltransferase 1 (LPCAT1) and activating DNA repair pathways." (PMID 35280689, 2022). "Using metagenomics, Liu and colleagues demonstrated that dysbiosis accelerated prostate cancer progression through upregulation of lysophosphatidylcholine acyltransferase 1 (LPCAT1), a key enzyme in the phospholipid remodeling pathway." (PMID 35330933, 2022). "Han found LPCAT1 overexpression led to castration resistant prostate cancer cell resistance to treatment with paclitaxel." (PMID 36307879, 2022). "The expression of LpCat1 was obviously increased in various tumors including prostate cancer, gastric cancer and breast cancer." (PMID 34178664, 2021). "Our previously study shown that Lysophosphatidylcholine Acyltransferase1 (LPCAT1) is overexpressed in castration resistant prostate cancer (CRPC) relative to primary prostate cancer (PCa), and androgen controls its expression via the Wnt signaling pathway." (PMID 33137125, 2020). "To date, LPCAT1 overexpression has been reported in hepatocellular carcinoma, colorectal adenocarcinoma, and prostate cancer and has been described as contributing to cancer progression, metastasis, and recurrence." (PMID 25803864, 2015). "Additionally,LPCAT1 plays a pro-tumorigenic role in tumor development and progression in prostate cancer and oral squamous cell carcinoma." (PMID 35880567, 2022). "Referring to the roles of LPCATs in tumors, LPCAT1 were always applied and investigated in tumor models, results showed that the levels of LPCATs were sharply upregulated in colorectal cancer, prostate cancer, etc., which suggested LPCAT1 prompted the growth and metastasis of tumors." (PMID 32733803, 2020).
prostate carcinoma (continued). "A recent study reported that it could convert androgen precursors into active androgens to promote the development of prostate cancer, and Ruminococcus could also promote the progression of prostate cancer by upregulating the expression of LPCAT1 and DNA repair proteins in prostate tissues." (PMID 38163068, 2023). "Recently, lysophosphatidylcholine acyltransferase 1 (LPCAT1), a lipid metabolic enzyme, was reported to be overexpressed and to function as a tumor-promoting role in several types of cancers, such as prostate cancer, gastric cancer, and liver cancer 10-12." (PMID 35399731, 2022). "The expression level of one of these enzymes, lysophosphatidylcholine acyltransferase 1 (LPCAT1), a key enzyme in Lands' cycle remodeling pathway, correlated with the progression of prostate cancer." (PMID 23152813, 2012).
breast carcinoma (19 papers, 2015 to 2025). "To broaden our knowledge on LPCAT1 as a biomarker in breast cancer we tested 2,197 breast cancer samples for LPCAT1 expression and analyzed associations with histologically and molecularly defined cancer subgroups as well as follow-up information." (PMID 31533087, 2019). "It is concluded that LPCAT1 overexpression is linked to adverse tumor features and poor prognosis in breast cancer." (PMID 31533087, 2019). "More precisely, ZNF217 might interfere with the lysophosphatidylcholine acyltransferase 1 recently implicated in breast cancer progression and metastatic dissemination." (PMID 26431164, 2015). "Hence, cellular levels of LPC and PC could predict the risk of breast cancer, and targeting LPCAT1 can add a new therapeutic approach for breast cancer." (PMID 35888767, 2022). "At present, studies on LPCAT1 and tumor resistance have been reported in lung adenocarcinoma and breast cancer." (PMID 40404896, 2025). "Among the mapped genes, high expression of LPCAT1 gene plays an important role in breast cancer progression." (PMID 37550674, 2023). "Another study showed that LpCat1 was expressed at least in normal breast tissues, relatively elevated in fibrocystic breast tissues, and most expressed in primary breast cancer tissues." (PMID 34178664, 2021). "The overexpression of LPCAT1 has been described in several cancers and the LPCAT1 protein was also significantly upregulated in primary breast carcinoma tissues compared with normal breast tissues." (PMID 34439324, 2021). "Since the staining intensity of LPCAT1 in normal breast glands was usually moderate, these data suggest that LPCAT1 is overexpressed in about 15% of breast cancers." (PMID 31533087, 2019). "In summary, our data identify LPCAT1 expression as a prognostic biomarker with potential clinical utility in breast cancer." (PMID 31533087, 2019). "Our data identify and validate high LPCAT1 expression as a strong prognostic biomarker for early tumor recurrence in breast cancer." (PMID 31533087, 2019). "LPCAT1 expression varied between histological breast cancer subtypes." (PMID 31533087, 2019). "A recent study on a cohort of 80 patients has suggested that up-regulation of LPCAT1 in breast cancer may contribute to tumor progression and predict early tumor recurrence." (PMID 31533087, 2019). "Lysophosphatidylcholine acyltransferase 1 (LPCAT1) converts LPC to PC and it is overexpressed in breast cancer with poor prognosis, which demonstrates that a higher level of PC is associated with a high risk of breast cancer." (PMID 35888767, 2022). "Moreover, lysophosphatidylcholine acyltransferase 1 (LPCAT1), which catalyzes the conversion of LPC to PC, is overexpressed in different tumors including breast cancer." (PMID 38646441, 2024). "Our data are consistent with a previous study by Abdelzaher and Mostafa comparing LPCAT1 expression in 80 breast cancers of NST and 30 non-neoplastic epithelial breast tissues." (PMID 31533087, 2019).